G6PD (glucose-6-phosphate dehydrogenase)
Diseases named in the same sentence as G6PD in open-access papers (continued):
Sharing a sentence is not in itself a finding about the gene and the disease.
cancer (continued). "In the majority of cancer types, G6PD is overexpressed to support cancer cell survival, growth, proliferation, metastasis, and invasion." (PMID 39726786, 2024). "This is in line with previous studies on malignancies as the upregulation of G6PD in cancers has been discussed frequently." (PMID 38022614, 2023). "We examined the variations in G6PD expression in 33 different types of cancer and assessed the prognostic significance of G6PD using public databases." (PMID 37601657, 2023). "Fourth, G6PD takes part in neuronal differentiation in the SH-S5Y5 cell line, meanwhile the aberrant activation of G6PD leads to enhanced cell proliferation and adaptation in many types of cancers." (PMID 37521469, 2023). "In cancer cells, glucose-6-phosphate dehydrogenase (G6PD), the key enzyme of the pentose-phosphate pathway (PPP) is up-regulated by hypoxia." (PMID 36851057, 2023). "G6PD participates in redox signaling, it affects survival, and death of cells, particularly in diseases such as cancer, and thus G6PD can be exploited as a potential drug target." (PMID 37049781, 2023). "In summary, the results of the present study indicated that the G6PD expression levels are higher in pan-cancer tissues relative to the expression level in normal tissues." (PMID 37601657, 2023). "Increased uptake of glucose and overexpression of enzyme glucose-6-phosphate dehydrogenase in cancer cells enable attaining sufficient ribose-5-phosphate and the reducing equivalents in the form of NADPH in the pentose phosphate pathway." (PMID 38136176, 2023). "The mechanism of G6PD in different cancer types needs to be further elucidated on the cellular and molecular levels." (PMID 37601657, 2023). "G6PD is highly expressed in different cancers, such as lung adenocarcinoma, breast carcinoma, colorectal cancer, hepatocellularcarcinoma, glioma and gastric cancer." (PMID 37049781, 2023). "Consistent with the hyper-proliferative nature of cancer cells, increased protein levels of glucose 6-phosphate dehydrogenase (G6PD) and transketolase (TKT) were documented in HBV- and HCV-related HCC patients." (PMID 37108625, 2023). "Evidence has shown that blocking G6PD activity can reduce cancer cell proliferation and increase apoptosis." (PMID 37601657, 2023). "The first rate-limiting step in the PPP pathway also plays a significant part in cancer development, and, in many cancers, there is upregulation of G6PD." (PMID 37049781, 2023). "Dysfunction of the G6PD enzyme in this pathway leads to cancer development as this enzyme possesses oncogenic activity." (PMID 37049781, 2023). "G6PD expression data were obtained from multiple data resources including the Genotype-Tissue Expression, the Cancer Genome Atlas, and the Tumor Immunity Estimation Resource." (PMID 37601657, 2023). "Drug sensitivity analysis showed that IC50 values of most identified anti-cancer drugs were positively correlated with the G6PD expression." (PMID 37601657, 2023). "Multiple studies have reported an elevation in G6PD levels in various types of human cancer, including HCC." (PMID 37627157, 2023). "G6PD is a rate-limiting enzyme in the pentose phosphate pathway (PPP), and G6PD overexpression is related to cancer prognosis and tumor metastasis." (PMID 37810967, 2023). "This study was designed to analyze the expression status and prognostic significance of G6PD in pan-cancer." (PMID 37601657, 2023). "The PPP enzyme G6PD is another fruitful target for cancer therapy, as it maintains the redox balance and PPP flux in the cells." (PMID 37762231, 2023). "Meanwhile, inhibition of G6PD can lead to accumulation of reactive oxygen species, induce endoplasmic reticulum stress, and slow the growth and migration of cancer cells." (PMID 36977688, 2023). "According to our investigations, upregulated expression of G6PD has been identified in many tumor cells and elevated G6PD expression levels are indicative of unfavorable clinical outcomes in cancer patients." (PMID 37601657, 2023).
cancer (continued). "The TCGA database positively correlated elevated abundance of G6PD with poor prognosis of cancer patients." (PMID 37491277, 2023). "Up-regulated ROS level induced by G6PD activation not only leads to out of control of cell growth and apoptosis of cancer, by also affects the immune microenvironment." (PMID 38098504, 2023). "As an adverse prognostic factor, G6PD has also been observed to promote the progression of many types of cancer." (PMID 37671041, 2023). "The top three cancers were UVM (R =0.4, P <0.001), LAML (R =0.34, P <0.001), and LGG (R = 0.32, P <0.001), in which G6PD expression was most closely associated with the Stromal Score." (PMID 37601657, 2023). "The results revealed that G6PD expression levels were relatively high in 25 types of cancer, except TGCT and LAML." (PMID 37601657, 2023). "The exposure of colorectal cancer cells to aspirin resulted in elevated acetylation of G6PD, which decreased its activity, contributing to the anti-cancer effects of aspirin." (PMID 36984785, 2023). "Meanwhile, KM curves confirmed that patients with high G6PD expression had a worse PFI than those with lower G6PD expression in many cancers, such as KIRC, LGG, MESO, and PRAD." (PMID 37601657, 2023). "Activation of the PI3K/AKT signaling pathway leads to higher G6PD activity, thereby enhancing metabolic activities and promoting cancer cell growth." (PMID 36768977, 2023). "This review will elucidate and update the vital characteristics of G6PD, the redox activity of G6PD, the role of G6PD in cancer development, the regulation of G6PD in cancer, and the potential of G6PD as a therapeutic target." (PMID 38139067, 2023). "G6PD is upregulated in several cancer types where it affects several cellular functions, creating a suitable and supportive environment for cancerous cell growth and survival." (PMID 37190196, 2023). "The expression of G6PD was elevated in many cancers, including HCC, which was positively correlated with tumors proliferation, migration and invasion." (PMID 37143953, 2023). "Remarkably, based on the results of this study, we found that G6PD expression was significantly positively correlated with infiltrating immune cells in most cancer types, especially in KIRC, LGG, LIHC, and PAAD, while negatively correlated with LUSC, STAD." (PMID 37601657, 2023). "The glycolytic metabolism of cancer cells is also controlled by glucose-6-phosphate dehydrogenase, the initial and rate-limiting enzyme in the oxidative phase of the pentose phosphate pathway." (PMID 38005711, 2023). "The natural molecule polydatin showed efficacy in inhibiting G6PD, followed by cell cycle block and apoptosis induction in cancer cells." (PMID 37762231, 2023). "In this study, we found that the IC50 value of most identified anti-cancer drugs was positively correlated with the G6PD expression level." (PMID 37601657, 2023). "In this study, we have selected and comprehensively evaluated the expression of four commonly known EMT markers (E-cad, N-cad, VIM, TGFβ1), and four unconventional EMT markers (α-SMA, AKR1B1, ITAV, G6PD), less studied in cancer in relation to the EMT process." (PMID 37174052, 2023). "Increasing evidence suggests that the expression and activity of G6PD have significant influences on different types of cancer." (PMID 38139067, 2023). "Most studies on cancer have concentrated on two small-molecule inhibitors of G6PD, namely 6-AN and DHEA." (PMID 38139067, 2023). "Further studies were necessary to characterize the specified molecular mechanism of G6PD degradation in various cancers." (PMID 37802999, 2023). "In this study, to demonstrate the biological role of G6PD in cancer, we utilized multiple databases to perform a visual pan-cancer analysis of G6PD." (PMID 37601657, 2023). "Several studies have shown that inhibiting G6PD using small-molecule inhibitors can reduce cancer progression and chemotherapy resistance." (PMID 38139067, 2023).
cancer (continued). "Several studies have showed that the splicing mechanism on its pre-mRNA regulates the activity of G6PD in various cancers." (PMID 38139067, 2023). "The roles of G6PD and PPP have been increasingly recognized in various cancers, and G6PD upregulation is correlated with poor prognosis." (PMID 37597521, 2023). "By knocking down these four candidate transcriptional factors using siRNA in cultured ccRCC cancer cells, we found the mRNA levels of G6PD and PGD decreased in SP1 knocking down cells." (PMID 37460463, 2023). "For example, silencing the PPP enzyme glucose-6-phosphate dehydrogenase (G6PD) reduces cancer cell proliferation and migration by inhibiting STAT3 and epithelial-to-mesenchymal transition (EMT) formation." (PMID 37762231, 2023). "Our analysis showed that G6PD expression was positively correlated with the Immune Score and Stromal Score in some cancers, especially in LAML, LGG, DLBC, and PAAD." (PMID 37601657, 2023). "The main regulatory enzymes of glycolysis, such as hexokinase-2, phosphofructokinase, aldolase, glucose-6-phosphate dehydrogenase, enolase, pyruvate kinaseM2, are known to be overexpressed in cancer cells." (PMID 38136176, 2023). "An increasing body of evidence in the last decade has documented the aberrantly high expression of G6PD in several types of cancers." (PMID 36271440, 2022). "The overexpression of G6PD helps cancer cells in their growth, proliferation, EMT, metastasis and invasion." (PMID 35207558, 2022). "To understand the variation in G6PD expression in different tissue-derived cancers, we analysed G6PD mRNA expression levels in tissues from 33 different cancers and their respective normal tissues using RNAseq data from the UCSC database." (PMID 35712981, 2022). "In conclusion, this review described the history and structure of G6PD, the effects of high G6PD expression (or high activity) on cancer, the regulation of G6PD expression from different aspects, and the role of G6PD in chemoresistance." (PMID 35207558, 2022). "Increasing the levels of G6PD mRNA expression levels facilitates the prediction of poor clinical outcomes in cancer patients, such as higher resistance to medication, migration, or proliferation of tumor cells." (PMID 35276059, 2022). "Aspirin can acetylate a variety of proteins in cancer cells, of which G6PD is its acetylation target." (PMID 35207558, 2022). "Because G6PD overexpression creates favorable conditions for cancer cells to thrive, it is of importance to better understand its regulation." (PMID 35806424, 2022). "The generation of NADPH is linked to other biochemical pathways, including a step in glycolysis and the pentose-phosphate pathway, which are dependent on glucose-6-phosphate dehydrogenase (G6PD), which has been implicated in cancer progression." (PMID 36473850, 2022). "For instance, the proteins encoded by MGST1/3, G6PD, GSR, and GPX2/4 play vital roles in glutathione synthesis, which serves as an antioxidant defender in cancer cells." (PMID 36133439, 2022). "Previous studies have demonstrated that the suppression of G6PD by 6-AN can restore the sensitivity of cancer cells to chemotherapy, so it is widely used in the treatment of cancers." (PMID 35207558, 2022). "Based on biochemical and cell-based findings presented here, Smilax china root extract targets G6PD and has an anti-cancer effect against HepG2 cells." (PMID 35991850, 2022). "Glucose-6-phosphate dehydrogenase activity is more advanced in cancerous cells than in normal cells, and blocking G6PD in cancer cells causes diminished proliferation and greater apoptosis in vitro." (PMID 35991850, 2022). "Specifically, G6PD is the rate-limiting enzyme of the pentose phosphate pathways, which is elevated in many cancers to promote tumor growth." (PMID 36010950, 2022). "Our analysis showed that G6PD is overexpressed in different cancer tissues, including HCC, and can be used as an HCC biomarker." (PMID 35712981, 2022).
cancer (continued). "As an effective inhibitor of the G6PD targeting PPP of cancer cells, DHEA reduces the NADPH levels, NADPH-dependent oxygen-free radical production and nucleic acid synthesis to inhibit tumor development." (PMID 35207558, 2022). "The aberrant activation of G6PD contributes to enhanced cell proliferation and adaptation in multiple cancer types." (PMID 36304446, 2022). "RRX-001 has a significantly G6PD activity inhibition effect on cancer cell lines, including HepG2, CACO-2 and HT-29." (PMID 35207558, 2022). "This is consistent with results in other cancers, which exhibited compensatory increases in isocitrate dehydrogenase activity, malic enzyme activity, and folate metabolism in response to reduced G6PD function." (PMID 35110412, 2022). "In cancer cells, G6PD was found to undergo O-GlcNAcylation, where the modification at Ser84 was essential for maintaining the enzyme’s activity, metabolic flux through the PPP, NADPH production, and increased levels of the ROS scavenger glutathione (GSH)." (PMID 36359905, 2022). "Elevated G6PD levels allow cancer cells to hijack and reprogram the intracellular metabolic pathways, which influences DNA replication, cell division, redox equilibrium, and proliferation to obtain an advantageous condition, especially during chemical therapy." (PMID 36271440, 2022). "Previously, inhibition of G6PD by DHEA has been mainly described in cancer cells, in which high G6PD activity is one of the drivers of cell growth and proliferation." (PMID 35676709, 2022). "The discovery that G6PD plays a key role in tumor cell metabolism has invigorated researchers to look for ways to specifically limit G6PD activity in cancer patients." (PMID 35991850, 2022). "As cancer cells can use PPP not only to metabolize glucose but also to produce antioxidants that enable glycolytic cancer cells to combat oxidative stress, more investigations on this pathway and its most important player, G6PD, have been conducted 36,37." (PMID 35173543, 2022). "At the transcriptional level, some transcription factors have been described to regulate G6PD expression in various cancers." (PMID 35806424, 2022). "What is more, G6PD also acts as a biomarker in diverse cancer in reflecting the clinical prognosis and chemoresistance." (PMID 35207558, 2022). "A few microRNAs can bind to mRNA of G6PD to degrade G6PD mRNA, influencing the proliferation, migration and invasion of cancer cells." (PMID 35207558, 2022). "Further studies are necessary to reveal more possibilities of G6PD in cancer because of its important role in both providing biosynthesis material and NADPH for redox equilibrium." (PMID 35207558, 2022). "Upregulation of G6PD level or activity is observed in many cancers, including pancreatic, cervical, gastric, colonic, and invasive breast carcinomas." (PMID 35806424, 2022). "Some kinds of microRNAs play a vital role in regulating the translation of G6PD, which is also involved in controlling cancer progression." (PMID 35207558, 2022). "The expression level of G6PD has been reported to increase in various cancer lesions, especially in cancers with advanced stages and metastatic disease, which is associated with poor treatment outcome 18-21." (PMID 35173543, 2022). "G6PD activity is elevated in several types of cancer, including LC, and it promotes cancer growth and development by maintaining intracellular redox homeostasis." (PMID 36336787, 2022). "The contributions of G6PD to the proliferation and survival of cancer cells occur at several levels." (PMID 36271440, 2022). "In this review, we will summarize the existing knowledge concerning G6PD and discuss its role, regulation and inhibitors in cancer development and chemotherapy resistance." (PMID 35207558, 2022).
cancer (continued). "Several signaling pathways are responsible for promoting G6PD expression or activity in cancer cells." (PMID 35806424, 2022). "Pan-cancer analysis showed that G6PD was significantly overexpressed in different tumour tissues, including HCC." (PMID 35712981, 2022). "Mounting evidence has demonstrated that G6PD expression is upregulated in several types of cancers and it promotes tumor progression." (PMID 36271440, 2022). "Molecular docking was used to screen Smilax china-derived compounds against G6PD to uncover novel natural scaffolds from Smilax china and to provide more opportunities for anti-cancer drug exploration." (PMID 35991850, 2022). "Reportedly, KRT6A is associated with cell proliferation and invasion, which drives cancer progression by upregulating glucose-6-phosphate dehydrogenase (G6PD) through MYC signaling pathway." (PMID 36505456, 2022). "Some results obtained in cancer tissues originating from the digestive system suggest that G6PD can counteract the programmed cellular death, as demonstrated by the lower expression of apoptotic markers Bcl-2 and Bcl-xL." (PMID 35565779, 2022). "Networks regulating G6PD are complicated in cancer cells and there are multiple cis/trans-regulatory elements controlling G6PD expression." (PMID 35207558, 2022). "Other modification enzymes need to clarify its role on G6PD and their effects in cancer development." (PMID 35207558, 2022). "G6PD regulatory networks are complex in cancer cells, and multiple cis/trans elements regulate G6PD expression." (PMID 35806424, 2022). "Knockdown of G6PD decreases cancer cell proliferation and glycolysis, while reducing the tumorigenic properties of gastric cancer cells." (PMID 35865630, 2022). "Of note, this seems to be at odds with the high activity of G6PD also seen in proliferative cancer cells." (PMID 35865630, 2022). "Developing more potential drugs aimed at G6PD is a promising but still long and rough way in cancer treatment." (PMID 35207558, 2022). "In resistant cancer cells, elevated expression of G6PD, AKR1B1 and GFPT2 counteracts the effects of ROS production as a prerequisite for cell survival and therapy resistance." (PMID 36463238, 2022). "Mounting evidence indicated that increased glucose flux towards PPP and overactivation of G6PD are common in many cancer types, including clear cell renal cell carcinoma, hepatocellular carcinoma, colorectal cancer, prostate cancer, and ESCC." (PMID 34354953, 2021). "Increased expression levels of G6PD mRNA results in poor clinical outcomes in cancer patients, including increased drug resistance, and tumor cell migration or proliferation." (PMID 34819088, 2021). "NRF2 plays a key role in tumorigenesis since it is usually upregulated in several cancer types triggering in turn upregulation of its target genes such as G6PD, malic enzyme 1 (ME1), and isocitrate dehydrogenase 1 (IDH1)." (PMID 34572981, 2021). "The other NADPH generating enzyme of the oxidative branch, 6-phosphogluconate dehydrogenase (6PGD), is also thought to modulate PPP flux in cancer cells in a similar manner to G6PD." (PMID 33946927, 2021). "G6PD has been found over-expressed and over-activated in several cancers, determining poor prognosis and chemoresistance, while its deficiency appears to decrease predisposition to cancer." (PMID 34880756, 2021). "Alternatively, under conditions of high reductive demand cancer cells have the capacity to divert glucose-6-phosphate dehydrogenase (G6PD) into the PPP pathway to maintain the constant generation of NADPH and nucleotides." (PMID 33834022, 2021). "Some specific types of cancers with notably high G6PD expression include ovarian, lung, renal, and oral cancers." (PMID 33946927, 2021).